BDNF (brain derived neurotrophic factor)
Diseases named in the same sentence as BDNF in open-access papers (continued):
Sharing a sentence is not in itself a finding about the gene and the disease.
psychosis (continued). "BDNF plays a vital role in development and activity of neurotransmission, which is consistent with animal studies showcasing BDNF involvement in psychotic disorders." (PMID 36767478, 2023). "Epigenetic regulation of BDNF has also been demonstrated to play a role in mental illness, as methylation of genes associated with SCZ, like BDNF, has been linked to psychosis." (PMID 35444632, 2022). "Given the fact that most patients with first episode psychosis respond well to antipsychotic treatment, we should be able to see change in BDNF levels in the whole sample if it were predictive of treatment." (PMID 35447946, 2022). "An epigenetic study also reported a correlation between major psychosis and DNA methylation of the BDNF gene." (PMID 35447946, 2022). "According to these findings, it can be assumed that peripheral BDNF levels can be considered as a potential biomarker for neurocognitive deficits in psychosis." (PMID 36281033, 2022). "Recently, publications on the relationship of BDNF and cognition in patients with first episode psychosis (FEP) have focused on drug-naïve patients." (PMID 34220575, 2021). "A meta-analysis of drug-free psychosis patients showed that BDNF increased after antipsychotic treatment in psychosis patients, however treatment response was not related to the increase of BDNF over the course of treatment." (PMID 33653423, 2021). "In recent years, researches have focused on the effects of BDNF on brain development in the early stages of psychosis." (PMID 33384622, 2020). "To date, several genes have been associated with the pathophysiology of psychosis, including neuregulin 1(NRG1), brain-derived neurotrophic factor (BDNF), and catechol-O-methyltransferase (COMT), along with the others." (PMID 31447712, 2019). "Nevertheless, variants of the BDNF and the NRG1 have been associated with dimensions of psychosis across diagnostic boundaries." (PMID 31447712, 2019). "The authors propose that reduced levels of BDNF are indicative for the early stages of the development of psychotic disorders, with a noticeable drop in peripheral levels of BDNF seen just before psychosis development." (PMID 31098654, 2019). "However, in BD, there were two studies reporting hypermethylation of the BDNF gene (exon 1 promoter) that was associated with pharmaceutical treatment and mood states, while another study reported a lack of differential methylation at this site in BD patients with a history of psychosis." (PMID 26809779, 2016). "Alemany and colleagues showed that the expression of subclinical psychosis in a general population sample was dependent on BDNF Val66Met genotype in those exposed to CT, a finding that remains to be replicated in independent samples." (PMID 24658422, 2014). "Two frequently studied genetic variants in psychosis research are the catechol-o-methyl-transferase (COMT) Val158Met and the brain-derived neurotrophic factor (BDNF) Val66Met polymorphisms." (PMID 24224001, 2013). "The results of the present clinical study show that plasma BDNF levels at 6 months after first hospitalisation for first episode psychosis (when patients have recovered from the acute episode) are positively associated with several cognitive domains." (PMID 23320462, 2013). "A recent study has demonstrated a strong relationship between plasma and CSF BDNF levels in first episode psychosis subjects." (PMID 22768299, 2012). "This is discordant with a previous study which reported the BDNF methylation status was dependent on genotype, and consequently had a differential effect on major psychosis." (PMID 23240009, 2012). "This grouping strategy reflects the structure of the available data and allows examination of the hypothesis that peripheral BDNF levels may vary in parallel with the clinical progression of psychosis." (PMID 41008288, 2025). "Title and abstract screening excluded 559 records that did not involve peripheral BDNF measurement in individuals at ultra-high risk for psychosis." (PMID 41008288, 2025).
psychosis (continued). "Reduced BDNF levels may have significant implications for neurodevelopmental abnormalities before the emergence of early functional deficits at the onset of psychosis." (PMID 37234686, 2023). "Therefore, the finding that peripheral blood BDNF levels are lower in patients with first episode psychosis seems robust." (PMID 35447946, 2022). "A recent preclinical study demonstrated that chronic methamphetamine use may interact with brain-derived neurotrophic factor (BDNF) Val66Met to remodel psychosis-related pathways in the mesocorticolimbic circuitry." (PMID 35741861, 2022). "A systematic review was conducted to examine whether BDNF level is different in patients with first episode psychosis (FEP) compared to health controls (HC) and whether it changes after treatment." (PMID 35447946, 2022). "Seven psychosis-implicated SNPs across five different genes (proxies of ZNF804A-rs1344706, CACNA1C-rs1006737, BDNF-rs6265, DISC1-rs2793092, DISC1-rs11122319, NRG1-rs6994992 and NRG1-rs35753505 itself) were examined in our independent sample for effects on brain volume." (PMID 36168994, 2022). "This suggests that BDNF levels are reduced at the onset of psychosis and that a psychological intervention could restore the plasma concentrations of this neurotrophic factor." (PMID 34299697, 2021). "It has also been shown that neurotrophic factors, including the brain-derived neurotrophic factor (BDNF), responsible for neuroplasticity in the human brain, plays a moderating role in the development of psychosis and PLEs in individuals exposed to psychosocial stress." (PMID 33925151, 2021). "There is also consistent evidence that a history of childhood trauma might be associated with global DNA hypomethylation and reduced expression of the BDNF gene in patients with psychosis." (PMID 31998156, 2019). "In male patients, cannabis use was associated with earlier age of psychosis onset, regardless of the BDNF Val66Met genotype." (PMID 28822116, 2018). "The present study investigated whether synergistic effects of CT and BDNF/FKBP5 genotype influenced two proxies of hippocampal integrity in a large sample of individuals with psychotic disorder and siblings." (PMID 24658422, 2014). "Patients with psychosis also show reduced brain-derived neurotropic factor (BDNF) levels both in the brain, and in serum and plasma, which may be related to their cognitive performance." (PMID 24409157, 2014). "Childhood trauma may thus represent a significant factor influencing cognitive function in psychosis, mediated through an effect on BDNF." (PMID 24409157, 2014). "Our finding of a positive association between BDNF levels and cognition in FEP patients who have recovered from an acute episode of psychosis may be partly due to the effects of pharmacotherapy on BDNF levels in these patients." (PMID 23320462, 2013). "Furthermore, Hh signalling has been associated with neurogenesis, as it enhances BDNF secretion, which has been considered a neuropathophysiological correlate of psychosis since reduced BDNF levels have been reported in the serum of patients with first-episode psychosis compared to healthy subjects." (PMID 38920990, 2024). "Many factors may contribute to differences in BDNF levels, such as differences in disease status, test material (plasma vs. serum), duration of untreated psychosis, age of onset, duration of disease, physical activity, and differences in the ethnic origins of study subjects." (PMID 37234686, 2023). "However, despite growing evidence for a role of BDNF in the development of addiction and psychosis, little progress has been made in determining the mechanisms involved in the contribution of BDNF to these diseases and how attenuated BDNF signalling impacts dopamine-driven behaviours." (PMID 37626786, 2023).
psychosis (continued). "This may lead to psychosis via distinct biological alterations such as: abnormal DNA methylation, hypothalamic–pituitary–adrenal axis dysregulation, decreased levels of brain-derived neurotrophic factor or subclinical pro-inflammatory in parallel to hippocampus and amygdala structural changes." (PMID 37563729, 2023). "However, the involvement of D3 receptors in the role of BDNF in psychosis progression and the mechanisms through which perturbed signalling occurs, remain largely unknown." (PMID 37626786, 2023). "Biological processes that link victimisation with an increase in psychosis risk include hyperactivation and sensitization of the hypothalamic–pituitary–adrenal (HPA) axis, decreased hippocampal volume, reduced brain-derived neurotrophic factor (BDNF) and increased dopamine release." (PMID 28861657, 2017). "Five studies compared peripheral BDNF levels between UHR individuals and patients with psychotic disorders (FEP or CS)." (PMID 41008288, 2025). "Findings across the eight studies included in this review were mostly inconsistent, and no discernible pattern in peripheral BDNF levels among ultra-high-risk groups could be identified when compared with healthy controls or individuals with established psychotic disorders." (PMID 41008288, 2025). "BDNF and GDNF, the most extensively investigated neurotrophins related to psychotic disorders, play a key role in cognitive processes." (PMID 39886050, 2024). "The aim of the present study was to gain a better understanding of the role of BDNF and D3 receptors in the effects of chronic METH on endophenotypes of psychosis." (PMID 37626786, 2023). "The aim of the present study was to gain a better understanding of the role of brain-derived neurotrophic factor (BDNF) and dopamine D3 receptors in the effects of chronic methamphetamine (METH) on prepulse inhibition (PPI), an endophenotype of psychosis." (PMID 37626786, 2023). "Taken together, they do not support any clinical application of peripheral BDNF levels in the early identification or management of psychosis." (PMID 41008288, 2025). "This absence of clear prognostic utility is consistent with broader literature that has examined peripheral BDNF as a potential clinical biomarker, yet has not produced conclusive evidence for its role in predicting psychosis." (PMID 41008288, 2025). "No participants transitioned to psychosis during the study period, and no clear clinical correlates of BDNF change were identified." (PMID 41008288, 2025). "We collected available data showcasing the influence of antipsychotic and non-pharmacological treatments, in patients suffering from psychotic disorders, on clinical conditions and BDNF levels in serum or plasma." (PMID 36767478, 2023). "In this section, we would like to investigate the role of BDNF in different types of non-pharmacological treatments used in psychotic disorders." (PMID 36767478, 2023). "A study using aripiprazole as a method of treatment reported a negative correlation between the duration of psychosis and plasma BDNF levels." (PMID 36767478, 2023). "The interaction of BDNF Val66Met and MTHFR C677T may reduce the hippocampal size in both healthy controls and patients with first-episode psychosis." (PMID 35834596, 2022). "Brain-Derived Neurotrophic Factor (BDNF), CACNA1C, NRG1, and FKBP5 are all additional candidate gene examples of a genetic link between stress, childhood adversity, and psychosis." (PMID 34946799, 2021). "The main effect of the BDNF Val66Met genotype on age of psychosis onset was not significant in the whole group as well as in males and females." (PMID 28822116, 2018). "So far, the effect of BDNF/FKBP5 by CT interactions on hippocampal volume in the context of psychosis has not been investigated." (PMID 24658422, 2014). "Plasma BDNF levels have a significant negative correlation with positive symptoms at psychosis onset." (PMID 23320462, 2013).
psychosis (continued). "Plasma BDNF levels show significant negative correlation with positive symptoms at psychosis onset." (PMID 37712092, 2023). "On the other hand, the novel tendency represented by the RDoC model to be able to study biomarkers in patients with psychosis as a group, instead of using the traditional diagnostic categories of the DSM or the ICD, does not seem to have permeated the field of study of BDNF and cognitive symptoms." (PMID 34220575, 2021). "There are also studies showing lower levels of peripheral blood brain-derived neurotrophic factor (BDNF), elevated levels of pro-inflammatory cytokines, more pronounced metabolic alterations, and altered DNA methylation profiles in patients with psychosis and a history early-life traumatic stress." (PMID 31998156, 2019). "In addition, risperidone is effective for use in steroid psychosis patients with PN, and improvement of psychotic symptoms in the patient was independent of serum BDNF levels." (PMID 22269819, 2012).
breast cancer (70 papers, 2009 to 2025). A primary or metastatic malignant neoplasm involving the breast. "The brain‐derived neurotrophic factor (BDNF) gene, influenced by DNA methylation and genetic profiles, has been independently linked to suicidal ideation in patients with breast cancer." (PMID 40387308, 2025). "In a female breast cancer patient cohort, Patani, Jiang, and Mokbel concluded that higher BDNF expression was significantly associated with poorer survival rates and adverse prognosis." (PMID 39648800, 2024). "Previous studies have suggested that suicidal ideation in breast cancer patients is particularly linked to genetic characteristics (brain-derived neurotrophic factor methylation, BDNF met allele)." (PMID 34786429, 2021). "The recombinant adeno-associated viral vector-mediated overexpression of BDNF was also used to reduce angiogenesis and decrease the proliferation of mouse breast cancer cells to prevent their metastasis." (PMID 33574842, 2021). "When studying the genetic factors of BDNF in women with breast cancer, it turned out that being a BDNF Met allele carrier was a protective factor against CRCD within the scope of self-observed memory dysfunctions, multitasking, and verbal abilities." (PMID 34573187, 2021). "The aim of this study was to evaluate the associations of cytokines and BDNF among early stage breast cancer (ESBC) patients with different CRCI trajectories." (PMID 33985854, 2021). "High level of peripheral NGF and BDNF has been proven to be associated with ovarian and breast cancer, polycystic ovarian syndrome (PCOS), and endometriosis." (PMID 33329121, 2020). "BDNF/TrkB pathways activated microRNAs to act as prognostic and predictive biomarkers for detecting patients at a high risk of developing breast cancer." (PMID 32190687, 2020). "In agreement with that independent public data set analysis revealed an abundant loss of BDNF expression in primary breast cancer tissues compared with normal breast tissues." (PMID 25036590, 2014). "Although low-BDNF expression levels decreased risk for tumor relapse more than high-BDNF levels in breast cancer patients, the risk for early tumor relapse increases from loss of BDNF." (PMID 25309465, 2014). "Breast cancer patients with low BDNF expression have an decreased risk for tumor relapse compared with patients with high BDNF expression (multivariate hazard ratio (HR): 0.374, p<0.05)." (PMID 25036590, 2014). "While the relationship between levels of specific cytokines with BDNF in human studies remains largely inconsistent across conditions, we previously reported differential associations between cytokines and BDNF among breast cancer patients with different trajectories of CRCI." (PMID 40597835, 2025). "Interestingly, activation of PPAR-γ leads to an anticancer effect in experimental models of breast cancer, and high BDNF levels have been associated with breast cancer development and resistance." (PMID 37628772, 2023). "In addition, BDNF/TrkB plays a critical role in promoting the recurrence of breast cancer after chemotherapy, cancer stem cell (CSC)-associated tumor-initiating potential, and chemoresistance." (PMID 32731498, 2020). "BDNF has been associated with several human neoplasms including ovarian, lung, prostate, hepatocellular, pancreatic, head and neck squamous cell carcinomas, and breast cancer." (PMID 28420987, 2017). "In addition, BDNF is found to increase cell viability and is associated with a reduction of the apoptosis of breast cancer." (PMID 28800782, 2017). "Interestingly, BDNF loss was abundantly found in breast cancer subtypes associated with poor prognosis, i.e. luminal B, HER2-enriched and basal-like breast cancer." (PMID 25036590, 2014). "In parallel researchers revealed that BDNF expression is significantly increased in breast cancer tissues compared to normal tissues and may be associated with unfavorable pathological parameters." (PMID 25036590, 2014).